IL1B (interleukin 1 beta)
Diseases named in the same sentence as IL1B in open-access papers (continued):
Sharing a sentence is not in itself a finding about the gene and the disease.
infection (continued). "Increasing evidence indicates that pro-IL-1β is processed into its biologically active form IL-1β during pyroptosis, which is a critical mechanism for host defense against infection." (PMID 33869229, 2021). "Analysis of proinflammatory cytokine/chemokine profiles during the acute phase of infection between days 14 and 16 post challenge showed marked increases of G-CSF, GM-CSF, IL-1β, IL-4, IL-8, IL-12/23 (p40), IL-18, MCP-1/CCL2, SCD40L, TGF-α, and VEGF." (PMID 34451491, 2021). "The cell culture supernatants were collected 24h post-infection to determine the levels of IL-1β and TNF-α exclusively in response to the intracellular bacteria." (PMID 34690967, 2021). "Among serum molecules identified in non-neurological and neurological diseases in the acute phase of the infection, 12 (IL-1β, IL-6, TNF, IL-2, IL-7, IL-17A, IL-15, IFN-α, IL-5, IL-13, IL10, and GM-CSF) were shared by both networks." (PMID 33776990, 2021). "IL-1β belongs to pro-inflammatory cytokine which is crucial to host-defense mechanism against infection." (PMID 34447698, 2021). "At 12 h post-infection, total cellular RNAs were extracted and the viral RNA accumulation as well as the mRNA levels of 5 inflammatory cytokines, such as IL-6, IL-1β, TNF-α, TGF-β and IL-10, were examined using qRT-PCR." (PMID 34335977, 2021). "The IL-1β is typically activated in macrophages after inflammasome sensing of infection or danger, leading to caspase-1 processing and driving inflammation after the release from macrophages." (PMID 34066479, 2021). "Considering that IL-8 is a major ET inducer in PMNs and IL-1β is a key mediator of the inflammatory response that attracts MΦs to the infection site, we analysed the levels of both cytokines in the supernatant." (PMID 33815401, 2021). "The inflammation response is a hallmark of host defense upon pathogenic infection in fish; as expected, we observed a significant increase in the expression of pro-inflammatory cytokines tnfa, il1b, il6, and cox2 upon infection with IPNv." (PMID 34768822, 2021). "Clones of DH82 cells lacking the caspase-1/-4 gene showed similar responses (cell death and IL-1β production) to WT DH82 cells after infection with S. Typhimurium, or stimulation with NLRP3-activating concentrations of nigericin." (PMID 34433041, 2021). "The results showed that the secretion of IL-1β was partially dependent on activation of NLRP6 inflammasome during macrophages infection with S. pneumoniae." (PMID 33918100, 2021). "Compared with WT, the T12D mutant had a significant increase in the expression of TNF-α at various time points, starting from 12 h after infection, whereas the IL-1β expression was slightly improved as compared to that of the WT." (PMID 33868202, 2021). "The production of IL-1B is promoted by platelets after infection with DENV, and the synthesis of IL-1B-containing microvesicles is induced by DENV, which ultimately increases vascular permeability." (PMID 34394108, 2021). "Treatment of Calu‐3 with IL‐1β during infection significantly increased induction of both ISGs and pro‐inflammatory cytokines, compared to their induction by virus alone." (PMID 34101213, 2021). "Levels of IFN-γ, TNF-α, and IL-1β were significantly reduced after 7 days of infection in the cultures treated with decitabine, but the quantification of IL-10 remained unchanged, suggesting an increase in anti-inflammatory ratio and control of inflammation." (PMID 33921194, 2021). "These cells respond by releasing inflammatory cytokines such as TNF-α, IL-1β, and IL-6, aiming to eradicate the infection and maintain homeostasis." (PMID 33731173, 2021). "Other biomarkers are considered specific for infection, such as interleukin 1 beta (IL-1) or Krebs von den Lungen-6 glycoprotein (KL-6)." (PMID 34945746, 2021).
infection (continued). "Nonetheless, even though neutrophils do not succumb to rapid cell death by pyroptosis, they do continue to release pro-inflammatory IL-1β at the site of infection to promote inflammation and direct the immune response." (PMID 34276697, 2021). "This regulation is required to limit the levels of TNF-α, IL-1β and IL-6 in the skin after infection." (PMID 34006861, 2021). "When comparison was made between different serotypes and primary/secondary infection, significant difference was observed in cytokines IL-1β, IL-2, IL-6, IL-8, IL-12, TNFα, IFNγ, GM-CSF, and IP-10." (PMID 34447698, 2021). "Further genes pointing towards NF-κB signalling during infection, such as il1b, il23a, nfκbia, tcim and zc3h12a, were also found to be induced by the bacteria in this study in presence or absence of the Erk1/2 inhibitor." (PMID 34863201, 2021). "On the other hand, in J774.G8 monocyte/macrophage cells, infection with WR-Luc induced a decrease in the levels of IL-1β mRNA (to 20% of mock-infected cells), while WR-IRF3 preserved them." (PMID 34696416, 2021). "Interleukin-1 beta is a proinflammatory cytokine that varies in transcription and protein expression during infection depending on the pathogen." (PMID 33652244, 2021). "The YopJ-regulated PGE2 and IL-1β synthesis are of physiological importance to the host response to infection." (PMID 34319170, 2021). "In the lung, the IL-1β mRNA expression in group IV decreased gradually from day 1 to 7 post-infection." (PMID 34988139, 2021). "The current results indicate that the capacity of candidalysin to induce IL-1β production is dependent on the anatomic site of infection." (PMID 33471869, 2021). "Defensin 1 limited the expression of IL-1β and IL-8 at both post-infection time points and both MOI values, as determined by qRT-PCR." (PMID 33843461, 2021). "The fluctuation in WBC count and TNF-α, IL-6 and IL-1β content in rat blood during the first week after infection were also monitored." (PMID 34521472, 2021). "What’s more, either SARS-CoV-2 or it’s variants infection, Meplazumab treatment had a favorable therapeutic effect on the downregulation of cytokines and chemokines at 6 d.p.i., such as IL-6, IL10, IL1b, CCL2, CXCL1, CXCL2, IFN-γ, IL-17, and CyPA." (PMID 34564690, 2021). "The results showed that the anti-infection effect of SB10 addition was eliminated by il1b interference (SB-il1b siRNA)." (PMID 34899717, 2021). "IL-1β is a proinflammatory cytokine, which affects the differentiation of T cells and enables the transmigration of immunocompetent cells to infection sites." (PMID 33647718, 2021). "Mice were infected with 105 PFU of HKx31 and intranasally treated with neutralizing anti‐IL‐1β or control IgG antibodies from day 1 or day 3 following infection." (PMID 33834544, 2021). "Specifically in the module, we find genes induced in response to infection such as IL1B, TNF, IL6, IL12B, NFKBIA, JUN, and MAP3K8, which are related to Toll-like receptor signalling (Appendix B)." (PMID 33498280, 2021). "IL-1β promotes inflammation by inducing the expression of proinflammatory genes, by recruiting immune cells to the site of infection, and by modulating infiltrating cellular immune-effector action." (PMID 33158978, 2021). "IL-1β and IL-18 levels were significantly increased in the peritoneal fluid of Mint3–/– mice 3 days after LM infection." (PMID 33854054, 2021). "While these metabolic changes have been extensively detailed in macrophages responding to LPS in vitro, infection with live P. aeruginosa also results in increased succinate accumulation and production of IL-1β in the murine lung." (PMID 34899759, 2021). "Conversely, overexpression of the inner mitochondrial membrane protein uncoupling protein 2 alters the MMP and reduces IL-1β secretion during infection." (PMID 34482801, 2021). "IL-1β is produced in response to infection and injury, and its accumulation leads to intramuscular inflammation after eccentric exercise." (PMID 34090451, 2021).
infection (continued). "As expected, IL-1β was low in the brains of uninfected mice but rose sharply in WT mice at days 1 and 3 post-infection." (PMID 33524073, 2021). "In our study the phosphorylation of NF-ĸBp65 enhanced expression of IL-6, TNF-α and IL-1β, 24 h post-infection." (PMID 34233673, 2021). "The activation of these signal pathways leads to the secretion of cytokines such as TNF-α and IL-1β, followed by the recruitment of more inflammatory cytokines to the infection sites by chemokines." (PMID 35069594, 2021). "Macrophages and NK cells are critical innate cell effectors in Xenopus host response during early stages of FV3 infection, and increased expression of IL-1β, TNF-α, Mx1, and IFN-γ genes was detected in infected tissues and leukocytes of adult frogs." (PMID 34675918, 2021). "Inhibition of FAK in THP-1 macrophages increased production of TNF-α and IL-1β upon infection with Mtb compared to control THP-1 macrophages, whereas FAK overexpression blocked the production of TNF-α and IL-1β." (PMID 34745115, 2021). "RAW264.7 cells and BMDMs infected with rMS::pMV261-Rv0927c induced a decrease in IL-6, TNF-α, and IL-1β expression, compared with those infected with rMS::pMV261 at 6, 24, and 48 h post-infection." (PMID 34531869, 2021). "As previously highlighted, the virulence factors SpeB and Alp 1 secreted during infection by S. pyogenes and A. fumigatus respectively activate IL-36γ, and SpeB has been shown to activate extracellular pro-IL-1β." (PMID 35003136, 2021). "IL-1β is a crucial inflammatory-response mediator that is central to host responses to infection and injury." (PMID 34945535, 2021). "In our study, we observed that inhibition or knockdown of NLRP3 markedly blocked H2-induced Casp1 activation and mature IL-1β secretion and also had a significant effect on cell death, indicating that H2 infection activated the NLRP3 inflammasome pathway." (PMID 34009097, 2021). "Low-infected individuals, however, with moderate il1b and tnfa responses, are able to control parasitaemia and to recover from the infection." (PMID 34114560, 2021). "In our study, ST2-/- mice decreased the concentration of IL-5 and increased IL-33, IL-13 and IL-17 in the initial stage of infection, and with 63dpi in addition to IL-33 and IL-17, also increased IL-1β concentration." (PMID 34324507, 2021). "IL-1β is an essential cytokine in innate immunity as one of the first signals in plasma in response to infection." (PMID 33562074, 2021). "IL-1β induces other cytokines including IL-1β itself, IL-1RA, TNFα, IL-6, and chemokines and adhesion molecules to promote early recruitment of neutrophils and other immune cells to infection sites." (PMID 33571211, 2021). "All genes in this category, except for the three antiviral genes, exhibited infection level-dependent up-regulation (e.g. tlr5a, campb, il8a, il1b, saa5, c3a) or down-regulation (i.e. gsn, pgds)." (PMID 35035387, 2021). "IL-1β, a potent pro-inflammatory cytokine facilitating host defense responses to infection, was used to activate IRAK1." (PMID 34906138, 2021). "We observed that infection with each strain induced a unique pattern of release of IL-1β and IL-18, implying that their engagements of inflammasomes are distinct." (PMID 35004352, 2021). "IL-1β mRNA was gradually upregulated during the infection period on days 2 and 5 PI, and days 9 and 14 PI and significantly upregulated on day 5 PI (p < 0.001), plateauing on day 14 PI (p < 0.05)." (PMID 33441700, 2021). "IL-1β is secreted primarily by immune cells in situations of infection, cell injury, and inflammation." (PMID 33613789, 2021). "HIF-1α stabilization reduces oxidative phosphorylation and increases glycolysis during infection with B. abortus and, likewise, enhances nitric oxide production, inflammasome activation and IL-1β release in infected macrophages." (PMID 33989349, 2021).
infection (continued). "The expression of il-1b, il-6, il-8, and il-10 was increased along with the infection time, where the expression of the four genes was higher at 33°C than at 18°C." (PMID 34566956, 2021). "In the present study, we compared the expression levels of the Th1-type cytokines IL-1β, TNF-α and IL-6 and the Th2-type cytokines IL-4 and IL-10 in susceptible host BALB/c mice and resistant host M. fortis on different days post-infection with S. japonicum." (PMID 34689797, 2021). "Infection with P. bovis or P. ciferrii increased the red fluorescence intensity of IL-1β in bMECs compared to the control." (PMID 34895324, 2021). "In vivo, treatment of mice with anti-IL-1β antibody prior to infection, abolished the increase in IL-1β that was seen after CDI in both plasma and colonic tissue of QQ and RR mice." (PMID 33718269, 2021). "SE did not affect the expression of IL-1β and IL-8 in the ileum, while in the caecum, the SE infection significantly increased IL-1β and IL-8 expression at 7 dpi (p < 0.0001 and p < 0.001, respectively)." (PMID 34944274, 2021). "In contrast to wild-type BMDMs, IL-1β secretion was significantly up regulated in Nox2-/-, Nos2-/-, and mCAT+/+ BMDMs during ΔpknF mutant infection." (PMID 34324582, 2021). "Altogether, the results indicate that NLRP3 and ASC are required for enhanced production of IL-1β and increased cell death during ΔpknF mutant infection." (PMID 34324582, 2021). "As expected, Ifnb1 was expressed only during infection with cytosolic, wild-type L. monocytogenes in both cell subsets, where Il1b was induced by TLR signaling during infection with both wild-type and Δhly L. monocytogenes infection." (PMID 34555127, 2021). "MFN2 is required for MMP homeostasis and IL-1β secretion after infection with RNA viruses, including influenza, measles, or encephalomyocarditis virus (EMCV)." (PMID 34482801, 2021). "Changes in the expression of cytokines IL-10, IL-4, IL-6, IL-1β and TNF-α were measured in BALB/c mice, the susceptible host of S. japonicum, and in M. fortis, the resistant host, before infection and on 3, 7, 10 and 14 dpi, respectively." (PMID 34689797, 2021). "Upon infection, we observed that disc cells did respond by upregulation of IL-1β production versus control samples, but the extent of expression varied between donors and in some cases required a higher MOI dose before significant increases were seen." (PMID 33652921, 2021). "Then, bacterial DNA activates AIM2 inflammasome, culminating in IL-1β production and control of infection both in vitro and in vivo." (PMID 35011636, 2021). "At 6, 24, 48, and 72 h post infection, blood samples were collected, and the serum levels of 10 cytokines (GM-CSF, IL-1β, IL-6, IL-10, TGF-β1, IFNγ, IL-4, IL-8, IL-12p40, and TNF-α) were assessed." (PMID 33665221, 2021). "(M–P) Gene expression analysis of Tnf (M), Casp1 (N), Il1b (O), and Il6 (P) in hypothalamus of young and old mice 8 days post-infection." (PMID 34151773, 2021). "After infection, the mRNA abundance of pro-inflammatory cytokines il1β and tnfα1 showed a significant difference between no-fever and fever individuals at 72 and 96 hpi (p-value p < 0.001; two-way ANOVA)." (PMID 34445566, 2021). "IL-1β production was high on the first day after infection, decreased on days 3 and 5, and showed an elevation at the end of the experiment." (PMID 34194400, 2021). "The biological activities of IL-1β and IL-18 and pyroptosis are mainly beneficial to the host during the infection process." (PMID 34276697, 2021). "Infection with P. ciferrii increased production of IL-1β, and IL-18 proteins and mRNAs in bMECs (P < 0.05), with more profound increases in bMECs infected with P. bovis (P < 0.05)." (PMID 34895324, 2021). "We next determined the role of caspase-1 in cell death and IL-1β secretion during infection with early and chronic isolates of P. aeruginosa using a THP-1 cell line that is sevenfold deficient in caspase-1 (THP-1-defCASP1)." (PMID 33664232, 2021).
infection (continued). "Il1b is one of the earliest expressed pro-inflammatory cytokines after activation of host PRRs, and enables organisms to respond promptly to an infection by inducing a cascade of reactions leading to inflammation." (PMID 35035387, 2021). "As expected, the expressed and secreted IL-1β levels were both significantly increased in PAMs after H45 infection at 10 MOI of infection or H45 OMVs stimulation at 10 μg/ml for 24 and 48 h." (PMID 34901247, 2021). "We found that in vivo Mφs isolated from DIO mice following MHV-A59 infection demonstrated decreased H3K9me3 at NFkB binding sites on the promoter(s) IL-1β, TNFα, and IL-6 compared to infected ND Mφs." (PMID 34479991, 2021). "After bacterial infection, IL-1β levels (detected at 8 h post infection) were sharply increased in the sera and peritoneal lavage fluids of the mice, but TAS treatment significantly reduced the IL-1β levels." (PMID 33679781, 2021). "For instance, treatments that focus on systemically negating IL-1β (i.e., anakinra, rilonacept, and canakinumab) have been reported to result in an escalated peril of infections." (PMID 34443594, 2021). "Neutrophils are also an important source of IL-1β because they are recruited in large numbers to sites of infection and inflammation." (PMID 34010648, 2021). "Production of IL-1β was lower after 4 h of infection than after 24 h and was significantly higher in PAMs infected with serovar 9 or 5 in the presence of IgG than without IgG at 24 h PI." (PMID 33968026, 2021). "The levels of pro-inflammatory cytokines (TNF-α, IL-1β, IL-6, and IL-8) were markedly higher after infection than those in the normal control group." (PMID 33670217, 2021). "EcoHIV-infection induced a prominent change in various neuroinflammatory markers (i.e., IL-1β, IL-6, TNF-α, and NF-κB) in the brain relative to the control animals." (PMID 34067600, 2021). "Defensin 1 also inhibited the bacteria-induced secretion of key cytokines IL-1β, IL-10, IL-12p70 and IL-23 at both post-infection time points and both MOI values, as determined by multiplex ELISA." (PMID 33843461, 2021). "The magnitude of spleen-tissue interferon (IFN)-α, IFN-β, IFN-γ, interleukin (IL)-1β and IL-6 expression induced by infection with the R543K mutant was significantly lower than those of JXSP2-4, but higher than those of the JXSP-310RdRp-infected ducklings." (PMID 34065634, 2021). "The increasing presence of activated immune cells during the early phase of infection, especially on day 3 p.i., further resulted in an abundant IL-1β and TNF-α expression in the spleen, similar to that measured in the heart." (PMID 34202636, 2021). "The release of IL-1β probably occurs in the first minutes of infection, as reported by other authors." (PMID 34835359, 2021). "Leukocytes fight infection and regulate immunity by secreting key immunomodulatory cytokines such as interleukin-1β (IL-1β), IL-6, IL-4, and tumor necrosis factor-α to promote tissue healing." (PMID 33846295, 2021). "IAV‐infected mice require ethical euthanasia on day 4 following infection and we next examined the intracellular expression of pro‐IL‐1β and pro‐IL‐18 at this timepoint." (PMID 33834544, 2021). "IL-1β is an acute phase IL that is produced early in infection and subsequently stimulates the release of IL-6 and IL-8 in mast cells." (PMID 34835359, 2021). "L. paracasei increases the levels of pro-inflammatory cytokines (IL1α and IL1β) and recruitment of immune cells before infection." (PMID 33897683, 2021). "Significantly higher secretion of CXCL1/KC, IL-1β, and IL-6 in the mouse lung upon infection with A. flavus conidia also suggest that A. flavus conidia are more efficiently cleared by the host as compared to A. fumigatus conidia." (PMID 33718288, 2021). "The protein expression levels of activated caspase-1 (p20) and mature IL-1β (mIL-1β) in the infection group were significantly higher than those in the control group." (PMID 34603335, 2021).